AXL (AXL receptor tyrosine kinase)
Diseases named in the same sentence as AXL in open-access papers (continued):
Sharing a sentence is not in itself a finding about the gene and the disease.
COVID-19 (continued). "The levels of ACE2 and AXL in the COVID-19 group were significantly lower than in the non-infected group, while SARS-COV-2 IgG was significantly higher in the COVID-19 group." (PMID 38799467, 2024). "Then, five important IADEGs (AXL, MKI67, CDKN3, BCL2 and PTGS2) for severe COVID-19 were screened by random forest analysis." (PMID 37113134, 2023). "Among, AXL, BCL2 and PTGS2 were clustered as a group with high expression in the normal sample and low expression in the COVID-19 sample." (PMID 37113134, 2023). "We then examined the relationship between TMPRSS2 and other targets for COVID-19 therapy, including ACE2, AXL, CTSL and FURIN." (PMID 35017320, 2022). "Several enzymes can be used as a target for COVID-19 therapeutics including PI3K ̧ mTOR, growth factor receptor, RAF, MAP2K2, FLT3, AXL, AKT, and matrix metalloprotease MMP2 and MMP9." (PMID 35251015, 2022). "FABP4positive macrophages express Axl receptor tyrosine kinase (Axl) and PROS1, which aids in reducing COVID-19’s severity." (PMID 34943795, 2021). "AM from healthy lungs showed high expression levels of AXL and PROS1, and these were markedly reduced in patients with severe COVID-19." (PMID 34143756, 2021). "When investigating the phenotype of DC1, a minor expansion of AXL+DC1, possibly related to type-I IFN signaling, was a general feature in COVID-19 along with decreased expression of the differentiation marker c-KIT." (PMID 33479167, 2021). "The scRNAseq data show that, in healthy human BALF, the FABP4+ macrophages express the TAM receptor AXL and the ligand for the TAM receptor MerTK (PROS1) and that these were profoundly repressed in severe COVID-19." (PMID 34143756, 2021). "Moreover, in severe COVID-19 cases, the serum ACE2, AXL, and SARS-COV-2 IgM levels reached a peak during days 8–15 before declining, whereas serum SARS-COV-2 IgG levels continued to rise, reaching a peak at day 31-180 days before decreasing." (PMID 38799467, 2024). "Thirdly, AXL and ACE2 play important roles in the severe progression of COVID-19." (PMID 38799467, 2024). "Meanwhile, existing research has not found that the differentially expression of AXL in healthy controls and patients with mild COVID-19." (PMID 37113134, 2023). "Alveolar type II epithelial cells (AT-II) and bronchial epithelial cells (Beas-2B) are the main cell types in the lung and are considered to be the main target cells of COVID-19 because they highly express ACE2 and tyrosine-protein kinase receptor UFO (AXL), respectively." (PMID 35287354, 2022). "Thus, it is likely a role for AXL in SARS-CoV-2 infection is not only relevant to lung cell populations, but ACE2-expressing tissues suspected to be affected by COVID-19 such as the heart and kidneys." (PMID 34797899, 2021). "Therefore, AXL, MKI67, CDKN3, BCL2 and PTGS2 might be key markers for occurrence and development of severe COVID-19." (PMID 37113134, 2023). "Furthermore, AXL, MKI67, CDKN3, BCL2 and PTGS2 as a marker combination could be used as potential markers to identify severe COVID-19 patients." (PMID 37113134, 2023). "Furthermore, assessing the expression of AXL and other receptors on remote tissues and assessing for viral SARS-CoV-2 load despite ACE2 inhibition would implicate these alternate receptors as playing central roles in the diverse clinical presentation of COVID-19." (PMID 35401519, 2022). "The levels of ACE2, AXL, SARS-COV-2 IgG/IgM were analyzed in patients with early COVID-19 (first week after laboratory-confirmed COVID-19), including 84 cases of non-severe and 64 cases of severe." (PMID 38799467, 2024).
renal cell carcinoma (27 papers, 2015 to 2025). "AXL overexpression is typically detected in a high percentage of renal cell carcinomas (RCCs) and is strongly associated with poor prognosis." (PMID 34877810, 2021). "Previous studies have demonstrated that exosomal lncARSR promotes sunitinib-resistant renal cell carcinoma by upregulating the expression of AXL and c-MET in recipient cells." (PMID 36765853, 2023). "Exosome-transmitted lncARSR functions as a sponge of miR-34/miR-449 to induce c-MET and AXL expression and mediates sunitinib resistance in renal cell carcinoma." (PMID 33154765, 2020). "Exosomal lncRNA activated in RCC with sunitinib resistance (lncARSR) was delivered to renal cell carcinoma to promote sunitinib resistance through sponging miR-34/miR-449, which further enhanced AXL and c-MET expression." (PMID 33072553, 2020). "In sunitinib-resistant renal cell carcinoma cells, the long non-coding RNA (lncRNA) lncARSR has recently been shown to sequester miR34a and facilitate AXL expression." (PMID 27834845, 2016). "Furthermore, both MET and AXL are involved in resistance to antiangiogenic agents in renal cell carcinoma; overexpression of these kinases was observed in HCC tumors that developed acquired resistance to sorafenib." (PMID 35062934, 2022). "Additionally, renal cell carcinomas, which are highly vascularized and have a sustained response to antiangiogenic therapies, have been shown to upregulate AXL expression." (PMID 34884986, 2021). "Studies have demonstrated that AXL expression is associated with antiangiogenic resistance, while the combination of AXL inhibitors with antiangiogenic agents could reduce vessel density in renal cell carcinoma patient-derived xenografts." (PMID 31684958, 2019). "In a separate study, it is found that lncARSR facilitates the expression of AXL and c-MET by competitively binding miR-34/miR-449, thereby enhancing resistance to sunitinib in renal cell carcinoma cells." (PMID 38100482, 2023). "Several early‐stage trials involving CAR T cells for renal cell carcinoma (RCC) are ongoing, assessing the feasibility of mainly two receptor tyrosine kinase targets: AXL, which plays diverse roles in tumor cell proliferation, migration, and survival (NCT03393936) and ROR2 (NCT03960060)." (PMID 35844304, 2022). "AXL signaling increased renal cell carcinoma expression of the pro-angiogenic factor S100A10, and an AXL inhibitor combined with a VEGF inhibitor decreased the growth of patient-derived xenografts and vessel density in mice." (PMID 34884986, 2021). "For example, lncARSR promotes sunitinib resistance via competitively binding miR‐34/miR‐449 to facilitate AXL and c‐MET expression in renal cell carcinoma (RCC) cells, and intercellular transfer of lncARSR by exosomes disseminated sunitinib resistance." (PMID 32578911, 2020). "These biomarkers were selected based on biological relevance to renal cell carcinoma, previous reports of prognostic significance, and the target profile of cabozantinib including both cabozantinib receptor targets (VEGFR2, MET, and AXL) and their ligands (VEGF, HGF, and GAS6)." (PMID 34364385, 2021). "Some studies have shown that exosomal lncRNA ARSR could competitively bind to miR-34 and miR-449 to regulate the expression of AXL, c-MET, and then promoted the drug resistance of renal cell carcinoma." (PMID 32587476, 2020). "Moreover, miR-217/HIF-1α/AXL signaling has been reported to be involved in lncRNA-HOTAIR-promoted renal cell carcinoma carcinogenesis, which provides a new target for the diagnosis and treatment of renal cell carcinoma." (PMID 35310917, 2022). "Although not initially developed as AXL-targeting agents, pan-TKIs that inhibit a spectrum of RTKs including AXL, most notably cabozantinib and sitravatinib, have shown promising activity in combination with ICB particularly in ICB-naïve renal cell carcinoma (NCT03937219, NCT03680521)." (PMID 35582229, 2020).
leukemia (26 papers, 2007 to 2025). A malignant (clonal) hematologic disorder, involving hematopoietic stem cells and characterized by the presence of primitive or atypical myeloid or lymphoid cells in the bone marrow and the blood. "Further investigations in a larger population or animal models focusing on the role of AXL in the pathophysiologic process of Flt3-mutated leukemia is warranted its significance on clinical outcomes." (PMID 33363015, 2020). "While AXL has been implicated in resistance to therapy in a variety of leukemia subtypes and therapeutic settings, the mechanisms of resistance vary." (PMID 27834816, 2016). "Even the shAXL knockdown with vehicle group had comparable leukemia burden and survival to the control group treated with 15 mg·kg−1 of gilteritinib, suggesting that AXL knockdown alone reduces leukemic progression." (PMID 39395205, 2025). "This upregulation is associated with ERK reactivation, and concurrent FLT3 and AXL inhibition diminishes adaptive ERK reactivation and sensitizes leukemia cells to FLT3 TKI treatment." (PMID 39395205, 2025). "Druggability evaluation of the 12 identified risk proteins revealed that three (AXL, CXCL8, and PDIA3) are already recognized as drug development targets for leukemia, cancer, and inflammation." (PMID 41463415, 2025). "Recent study in leukemia cells has found GAS6/AXL axis is required to skew macrophages toward a tumor-promoting tissue repair phenotype to establish a suppressive environment to prevent immune attacks." (PMID 37328828, 2023). "In leukemia cells, AXL expression is regulated by the activator protein 1 (AP-1), FOS and JUN heterodimers." (PMID 35572601, 2022). "This further supports other findings that state high AXL expression leads to a worse prognosis in leukemia patients." (PMID 28881658, 2017). "Furthermore, targeting AXL has been shown to decrease leukemia cell proliferation and improve responses to combination therapies, particularly in cases with persistent minimal residual disease." (PMID 40277842, 2025). "Due to its significant effect on AXL-positive osteomyeloid leukemia cells and TNBC cell models, it could be a promising regime for cancer treatment." (PMID 37328828, 2023). "AXL-RTK play a pivotal role in various cancers including leukemia." (PMID 34140003, 2021). "One of the receptor tyrosine kinases (RTKs), AXL, has become a novel target for leukemia therapy." (PMID 34140003, 2021). "Through the analysis of transcriptomic data of 701 leukemia and NB patient samples and cell lines, we revealed that the expression of RTK, such as KIT, FLT3, AXL, FGFR3, and NTRK1, is linked with HDAC class I. Although HDAC inhibitors have antitumor activity, they also have high whole-body toxicity." (PMID 34944663, 2021). "AXL signals through many of the same downstream oncogenic pathways as FLT3 so may serve as a bypass mechanism that allows leukemia cells to survive FLT3 inhibition." (PMID 29806049, 2017). "Besides its role in drug resistance, AXL is highly expressed in primary CD34+ leukemia stem cells and its expression is dependent on the breakpoint cluster region/abelson murine leukemia viral oncogene homolog 1 (BCR-ABL) protein level rather than its tyrosine kinase activity." (PMID 31694201, 2019). "AXL inhibition combined with FLT3 inhibition to decrease the ERK signal rebound and to exert greater anti‐leukemia effects than with either treatment alone." (PMID 39395205, 2025). "The transcription factor HIFα can promote AXL in renal clear cell carcinoma, and AP1 can promote AXL expression in leukemia." (PMID 32148495, 2020). "Cabozantinib (XL184) targets VEGFR2, c-MET, KIT (also known as CD117), AXL, and FLT3; and induces apoptosis in FLT3-ITD+ leukemia cells in a dose-dependent manner." (PMID 31694201, 2019). "In vivo, AXL inhibition resulted in prolonged survival of tumor-bearing mice and reduced the growth of CD34+ leukemia stem cells." (PMID 31694201, 2019).
leukemia (continued). "Our findings are consistent with the recent report showing that Gas6/AXL signaling stabilizes β‐catenin protein in an AKT‐dependent mechanism, thereby regulating self‐renewal of drug‐resistant leukemia stem cells." (PMID 30353671, 2018). "Previous studies showed that sitravatinib could significantly decrease AXL phosphorylation, which might also contribute to its efficacy against FLT3-ITD leukemia." (PMID 36691065, 2023). "We measured the expression of genes coding RTKs: FLT3, KIT exclusively in leukemia cell lines, PDGFRa, AXL in NB, NTRK1, FGFR3, INSR, ROR2, and RET in both NB and leukemia cells by qRT-PCR, which were top-scoring RTK-coding genes among leukemia and NB cell lines." (PMID 34944663, 2021). "Similarly, FLT3-ITD AML cells demonstrate constitutively active AXL and AXL inhibition leads to decreased FLT3 phosphorylation and induction of leukemia cell death." (PMID 29806049, 2017). "Finally the roles of both AXL and MERTK in leukemia have been well described, but less is known about TYRO3." (PMID 27834816, 2016). "Finally, as TYRO3, AXL, and MERTK are attractive therapeutic targets in leukemia, we will discuss recent advances toward introduction of small molecule inhibitors of MERTK and AXL into the clinic." (PMID 27834816, 2016). "AXL-Fc treatment led to decreased tumor growth and prolonged survival in subcutaneous AML xenograft models, demonstrating the potential therapeutic application of TAM RTK ligand traps in leukemia." (PMID 27834816, 2016). "ASP2215 trials are ongoing, both in newly diagnosed AML patients and relapsed/refractory populations; however, without regard for AXL expression, likely due to the current lack of biomarkers to predict response to AXL inhibition in leukemia." (PMID 27834816, 2016). "Additionally, AXL appears to regulate the persistence of leukemia stem and progenitor cells, independent of BCR::ABL1 activity, making it a potential therapeutic target even in TKI-resistant cases." (PMID 40277842, 2025). "AP-1-mediated regulation of AXL is not restricted to leukemia cells." (PMID 35572601, 2022). "Healthy non‐leukemic CD34+ cells and other leukemia cell lines with wild‐type FLT3 exhibited no induction of AXL protein levels when treated with FLT3 TKI, even with differing basal AXL levels across the different cells." (PMID 39395205, 2025).
osteosarcoma (25 papers, 2014 to 2025). A usually aggressive malignant bone-forming mesenchymal neoplasm, predominantly affecting adolescents and young adults. "Strikingly, our study uncovers CNK2-dependent ARF6 signalling as a novel mechanism underlying the pro-motility function of AXL in U2OS osteosarcoma cells." (PMID 37322019, 2023). "Taken together, linc00852 significantly increased in osteosarcoma tissues, and it was positively associated with tumor volume, metastasis, and the expression of AXL mRNA, and it functioned as an oncogene to facilitate osteosarcoma initiation and development." (PMID 32673448, 2020). "Receptor tyrosine kinase AXL has been found to be highly expressed in osteosarcoma and positively associated with poor prognosis." (PMID 32673448, 2020). "Clinically, linc00852 was significantly highly expressed in osteosarcoma tissues and positively associated with tumor volumes and metastases, which was also obviously related with AXL mRNA expression." (PMID 32673448, 2020). "AXL was highly expressed in osteosarcoma and positively associated with a poor prognosis." (PMID 32673448, 2020). "AXL‐associated exosomal linc00852 up‐regulated the proliferation, migration, and invasion of osteosarcoma cells, which would be considered as a new tumor biomarker and a special therapeutic target for osteosarcoma." (PMID 32673448, 2020). "Higher AXL expression in osteosarcoma patients is associated with poorer survival." (PMID 32984034, 2020). "AXL‐associated exosomal linc00852 may be considered as a new tumor biomarker and a special therapeutic target for osteosarcoma." (PMID 32673448, 2020). "AXL‐associated exosomal linc00852 may be considered as a special therapeutic target and a new tumor biomarker for osteosarcoma." (PMID 32673448, 2020). "AXL expression is also associated with metastasis in many cancer types, including osteosarcoma." (PMID 25528764, 2014). "To further explore the molecular mechanism of SNHG6, we validated the correlation between SNHG6 and AXL in osteosarcoma cells." (PMID 38194709, 2024). "Research has shown that AXL has the ability to facilitate the progression of osteosarcoma through the regulation of the PI3K/AKT signaling." (PMID 38194709, 2024). "The previous research has shown that lncRNA can regulate the progression of osteosarcoma through AXL." (PMID 38194709, 2024). "Surprisingly, attenuation of SNHG6 in osteosarcoma cells reduced the expression of AXL and p-AXL, and WB results showed that the phosphorylation of AKT was also affected (** P < 0.01)." (PMID 38194709, 2024). "Using osteosarcoma cells to decipher the underlying mechanism, we discovered a CNK2-dependent signalling axis, triggered by the RTK AXL, that coordinates the activity of ARF6, RAC1, and RHOA GTPases." (PMID 37322019, 2023). "It was found that AXL was expressed at high levels in human metastatic osteosarcoma cell lines, as well as in derived circulating tumor cells (dCTCs), which are cancer cells shed to the blood and founders of metastases." (PMID 38203403, 2023). "By using a small molecular inhibitor of AXL in vivo, it was demonstrated that AXL inhibition significantly reduced the homing of the osteosarcoma cells into the lungs, diminishing the number of pulmonary metastases." (PMID 38203403, 2023). "Meanwhile, the YAP/YAZ transcription activators cast a significant shadow over osteosarcoma by regulating epithelial–mesenchymal transition (EMT) via AXL and deeply influencing cellular differentiation, fate determination, and metastatic behavior." (PMID 38140058, 2023). "MiR-199a-3p has a targeting relationship with AXL and negatively regulates the progression of osteosarcoma through AKT signaling pathway." (PMID 35844793, 2022). "There were different tumor groups with different levels of AXL in osteosarcoma, which had different capabilities of invading vessels and forming distal metastases." (PMID 32673448, 2020).